HDAC2 (histone deacetylase 2)
Diseases named in the same sentence as HDAC2 in open-access papers (continued):
Sharing a sentence is not in itself a finding about the gene and the disease.
cancer (continued). "This overexpression of HDAC2 appears to be implicated in cancer through its aberrant recruitment to promoter of tumour suppressor genes leading to gene silencing." (PMID 27283986, 2016). "Our results demonstrated that repression of miR-31 contributes to transcriptional activation of HDAC2, and, thereby causes the acceleration of cell cycle transition of cancer cells through selective regulation of cell cycle components." (PMID 25797269, 2015). "HDAC2 encodes a protein that forms transcriptional repressor complexes playing an important role in transcriptional regulation, and in cancer." (PMID 25148247, 2014). "Although changes in HDAC2 expression have also been identified in a number of cancers, an inactivating frameshift mutation appears to leave cells more resistant to HDAC inhibitors (HDACi)." (PMID 25322459, 2014). "Among the PRCa genes expressed at the protein level are transcriptional regulators (Hdac2 and Hmga2), cancer-linked genes (Klf4 and Kit), and genes involved in glycolysis and pyruvate metabolism (Hk1, Eno2, and Pck2)." (PMID 22305566, 2012). "This further supports our first observation that HDAC2 is strongly associated with cancer stemness." (PMID 39063083, 2024). "The transcriptomic profiling indicated that class I HDAC members, including HDAC2, are positively associated with cancer stemness, while class IIA HDAC proteins, represented by HDAC7, show a negative correlation to cancer stem cell-like phenotypes in solid tumors." (PMID 39063083, 2024). "CK2 is mainly associated with and phosphorylates HDAC2 in cancer cell lines." (PMID 39357831, 2024). "Based on our findings linking high HDAC2 expression to adverse outcomes in HCC patients and identifying it as an independent risk factor for HCC, targeting HDAC2 with inhibitors may enhance anticancer strategies by suppressing cancer cell growth and autophagy." (PMID 39147759, 2024). "Specifically, HDAC2 is overexpressed, mutated, or abnormally recruited in cancer cells." (PMID 37528657, 2023). "Additionally, HDAC-2 expression in the neoplasm, was also shown to be associated with increased incidence of a carcinoma in situ component adjacent to the invasive carcinoma." (PMID 34441281, 2021). "Additionally, HDAC2 has the diagnostic power to differentiate between cancer and non-cancer diagnosis." (PMID 31121824, 2019). "In contrast to our present results, mounting evidence indicates that HDAC2 is aberrantly overexpressed in a variety of cancer tissues and implicated in the promotion of malignant phenotypes of certain cancer cells such as anti‐cancer drug resistance." (PMID 30868056, 2019). "Recent clinical results are indicative of associations between HDAC2 and cancer prognosis." (PMID 28538837, 2017). "A finding that needs confirmation in a larger association study isthe observation that the CAG insertion identified in the 5'UTR of HDAC2 could be associated with cancer predisposition." (PMID 16638127, 2006). "However, it is unknown whether the HDAC2 status of MSI cancers is linked to the expression levels of checkpoint kinases and enzymes that produce nucleotides and metabolize 5-FU, such as TS or ribonucleotide reductase (RNR)." (PMID 35608750, 2023). "Several studies have shown that various HDAC inhibitors such as SAHA and other hydroxamic acid derivatives increase cisplatin toxicity in cancer cells or can circumvent cisplatin resistance, supporting the association between the activity of cisplatin or carboplatin and the expression of HDAC2." (PMID 35008351, 2021). "As a class I HDAC, HDAC2 is often overexpressed in cancers and promotes malignancy through diverse mechanisms." (PMID 41408324, 2025). "It was suspected that HDAC2 regulates CNOT7 expression by regulating downstream cancer-related signaling pathways." (PMID 38985240, 2025).
cancer (continued). "Based on these findings, we conducted in vitro functional assays and demonstrated that HDAC2 enhances proliferation, migration, cancer cell stemness, and anti-apoptotic capacity in BCa cells." (PMID 41408324, 2025). "Among them, HDAC1 and HDAC2 are particularly significant in neural progenitors and are frequently overexpressed in neural-derived cancers." (PMID 40640468, 2025). "Analysis of CRISPR data from DepMap reveals weak overall dependencies of HDAC1 and HDAC2 across cancer cell lines, likely because one compensates in the absence of the other." (PMID 40479062, 2025). "HDAC2 plays a significant role in the development of many diseases, mainly involving cancer and neurodegenerative diseases." (PMID 38985240, 2025). "The discovery and development of selective HDAC2 inhibitors have great potential in the treatment of targeted cancer." (PMID 38985240, 2025). "Among histone deacetylases, HDAC1 and HDAC2 (Class I) showed reduced expression in carcinomas compared to normal tissues." (PMID 40590021, 2025). "A higher expression of HDAC2 is also found to be an important marker of poor prognostic factors in different types of cancer." (PMID 38337591, 2024). "Class I HDAC inhibitors, specifically HDAC2, is abnormally expressed in several cancers including ovarian." (PMID 38337591, 2024). "These insights not only deepen our knowledge of cancer pathophysiology but also open avenues for exploring personalized therapeutic strategies targeting HDAC2 in HCC." (PMID 39147759, 2024). "Differences in HDAC7 expression between patients with different immune subtypes are statistically significant for all tumors (except OV and COAD) and p-values are generally lower in comparison to HDAC2 differences in the same cancers." (PMID 39063083, 2024). "In contrast to tumors with high amounts of HDAC7 proteins, the transcriptome signatures of HDAC2-overexpressing cancers are significantly enriched with biological terms previously determined as stemness-associated genes." (PMID 39063083, 2024). "Given that HDAC2 is crucial for promoting autophagy in HCC and that autophagy is linked to cancer malignancy, we further examined the tumor-promotive function of HDAC2 and its connection to autophagy." (PMID 39147759, 2024). "Our research uncovered a significant association between cancer stemness and an elevated expression of class I HDAC family members, especially HDAC2, where the association was robust and universal regardless of the tested tumor type." (PMID 39063083, 2024). "PARP-1 and HDAC2 were overexpressed in various cancers and contributed to tumor progression through their roles in DNA repair, transcriptional regulation, and the maintenance of genomic integrity." (PMID 39199199, 2024). "By bioinformatics mining, HDAC2 expression was higher in the cancer tissues than that in the adjacent tissues in the TCGA-LIHC and ICGC-JP sets (p < 0.001)." (PMID 37171044, 2023). "HDAC1 and HDAC2 depletion rendered cancer cells hypersensitive to IR and resulted in diminished DSB repair capacity, particularly by nonhomologous end-joining." (PMID 37991020, 2023). "Irrespective thereof, the presence of HDAC2 in most cancer cells suggests that its expression is more beneficial than its loss in most tumor cells." (PMID 35608750, 2023). "HDAC2, a member of the class I HDACs, has been reported to play important roles in cellular proliferation, cell signaling, cancer initiation and progression, inflammation, and gene expression regulation." (PMID 36968022, 2023). "In synovial sarcoma, HDAC2 inactivation induced the degradation of the SS18-SSX driver oncoprotein to inhibit cancer cell proliferation." (PMID 36968022, 2023).
cancer (continued). "Patchouli alcohol is also known to have anticancer properties because it can inhibit the growth of cancer cells through the mechanism of inhibiting HDAC2 enzyme expression, downregulation of c-MYC, and activation of the NF-κB pathway." (PMID 36903266, 2023). "Given the fact that HDAC2 binds to CAGE, it is necessary to examine the presence of HDAC2 in the exosomes of cancer cells." (PMID 36968022, 2023). "It is noteworthy that the involvement of HDAC2 in tumorigenesis varies across different cancer types and is often complex and even contradictory." (PMID 37495623, 2023). "SFN reduces HDAC1, 4, 5, and 7 protein levels in cancer cells and inhibits class I HDACs, such as HDAC2, as well as class IIa HDACs, such as HDAC4, 5, 7, and 9, in 3T3-L1 adipocytes." (PMID 37298289, 2023). "In combination with public cancer databases and tissue microarrays, this study investigates the role of HDAC2 in HCC." (PMID 37171044, 2023). "HDAC2-derived peptides corresponding to these domains can also be developed as anti-cancer drugs for HDAC2/CAGE-expressing cancers." (PMID 36968022, 2023). "These genes can be employed as targets for developing anti-cancer drugs and will also make it easier to understand the mechanism of HDAC2-promoted cancer cell proliferation and anti-cancer drug resistance." (PMID 36968022, 2023). "Wogonin exerted anti-cancer effects by inducing the degradation of c-MYC, s-phase kinase -associated protein 2, HDAC1, and HDAC2." (PMID 36968022, 2023). "Spalt-like transcriptional factor 4 (SALL4), a stem cell marker, was reactivated in several cancers and interacted with HDAC2." (PMID 36968022, 2023). "Selected compounds were evaluated against several cancer cell lines and docked into HDAC2 and HDAC8." (PMID 37570656, 2023). "Recent evidence has just pointed out that the HDAC2 inhibitor (HDAC2i), which has been proven to exhibit an anti-cancer effect, can act as a sensitizer for ICIs therapy." (PMID 37764768, 2023). "Compounds 78 and 79 were most potent and had comparable activities to SAHA with regard to HDAC2 inhibition and potency against four cancer cell lines, respectively." (PMID 37570656, 2023). "The HDAC2 expression profile across cancer and normal tissues was detected by using the GENT2 platform." (PMID 37764768, 2023). "PARP1 maintains cellular functions, including DNA repair/maintenance of genomic integrity, DNA methylation, chromatin regulation, and histone modification and helps in the recruitment of HDAC1 and HDAC2 as chromatin modifications in cancer." (PMID 35059624, 2022). "These new findings suggest that the HDAC2/EZH2/miR-148a/PDK1 axis is a novel mechanism for regulating cancer development and is a potentially promising target for therapeutic options in the future." (PMID 35892859, 2022). "Histone deacetylase-2 (HDAC-2), which has been studied for a long time as a cancer treatment agent, converted monocyte MDSC to granulocyte MDSC, and the mechanism was suggested." (PMID 35185933, 2022). "Both HDAC1 and HDAC2 are involved in regulation of cell cycle, cellular senescence and cancer progression." (PMID 35563824, 2022). "HDAC-2 has been reported to play a significant role in various cancer entities, ranging from medulloblastoma, melanoma, lung cancer, and hematological malignancies, to pancreatic, colorectal, prostate, and urothelial cancer." (PMID 36294811, 2022). "We further investigated the involvement of HDAC2 in TRIB2‐driven cancer stemness and radioresistance." (PMID 34586732, 2021). "Activation of HDAC2 was found to epigenetically repress p21 expression, resulting in enhanced radioresistance and cancer stemness of ESCC cells." (PMID 34586732, 2021). "In summary, we identified a key regulatory METTL14‐miR‐99a‐5p‐TRIB2 feedback circuit that epigenetically represses p21 through Akt/mTOR/S6K1/HDAC2 to promote cancer stemness and radioresistance in ESCC." (PMID 34586732, 2021).
cancer (continued). "Vorinostat (HDAC2 inhibitor) and aminocaproic acid (PLAT inhibitor) both inhibited a SARS-CoV2 ‘prey protein’ and targeted a gene within the pathways in cancer and extracellular matrix (ECM)/ECM-associated proteins PES pathways, respectively." (PMID 33720009, 2021). "Class IIa HDAC-4 stained 44% of benign and 36% of malignant tumors, mostly with a nuclear pattern, while 4 cases (different from the ones mentioned for HDAC-2) showed a cytoplasmic pattern of staining (3 PAs and 1 SCC)." (PMID 33799478, 2021). "In cancer cells, SPHK2 associates with HDAC1 and HDAC2 in the transcription repressor complex, and S1P generated by SPHK2 binds to and inhibits HDAC1 and HDAC2, resulting in epigenetic regulation of gene expression." (PMID 34055895, 2021). "ESCC tissues and mucosal tissues (5 cm from cancer tissues) were collected, in which HDAC2, miR-503-5p and CXCL10 expression levels were tested." (PMID 33926524, 2021). "Histone deacetylase 2 (HDAC2), a member of the Histone deacetylase family, plays a vital role in various carcinomas." (PMID 33325150, 2021). "In the GSE15471 dataset, the expression of the genes (except HDAC2) was significantly elevated in PDAC cancer tissues compared to normal tissues (p < 0.01)." (PMID 32977589, 2020). "Since HDAC2 is known to have many redundant functions, it is classified as a less attractive marker for early cancer development." (PMID 33133158, 2020). "Valproic acid (VPA), an inhibitor of HDACs, binds to HDAC2 and enhances sensitivity to anti-cancer drugs." (PMID 32626712, 2020). "It is a novel antitumour depsipeptide that inhibits HDAC2 and restores the expression of genes aberrantly suppressed in cancer cells." (PMID 30737378, 2019). "Recently it was shown that antisense lncRNA EPB41L4A-AS1 in human cancer cells is responsible for the translocation of histone-deacetylase HDAC2 to the nucleolus due to the interaction with both HDAC2 and nucleophosmin (NPM1)." (PMID 31269716, 2019). "Five HDAC genes (HDAC2, HDAC4, HDAC5, HDAC10, and SIRT3) showed copy number loss in at least two cancer types." (PMID 30760718, 2019). "HDAC2 regulates the cell cycle and apoptosis of cancer cells, and gene editing of HDAC2 resulted in a more differentiated phenotype and increased apoptosis caused by augmented levels of p21." (PMID 31805977, 2019). "Cancer tissues (T) exhibited higher HDAC2 protein but lower miR-500a-5p expression levels compared with the corresponding non-cancerous controls (N)." (PMID 30737378, 2019). "In the current study, we investigated romidepsin, an HDAC1 and HDAC2 inhibitor, that has been used as an anticancer drug and is known to induce cancer cell cycle arrest, cancer cell differentiation, and cell death." (PMID 29731773, 2018). "It stimulates angiogenesis, binds to HDAC2 and confers resistance to anti-cancer drugs in various cancer cells." (PMID 30619741, 2018). "To confirm our results regarding the involvement of HDAC2 in promoting cancer stemness, we performed a silencing of HDAC2 using HDAC2 shRNA both in MG63 and Saos2 cells." (PMID 30509303, 2018). "Since HDAC (HDAC1, HDAC2) expression and activity are frequently increased in cancers and that epigenetics has been shown to be crucial in cancer biology, the project to use HDACis to fight cancer progression emerged more than 15 years ago." (PMID 29754883, 2018). "Depending on the cellular context, HDAC1 and HDAC2 can either exist in predominantly heterodimer form in both normal and cancer cells, function independently, or potentially act as homodimers in other cellular contexts such as in mouse fibroblasts." (PMID 28982113, 2017). "Eighteen HDACs were identified in mammals, among them class I HDAC family members that include HDAC1 and HDAC2, are localized in the nucleus and regulate some biological events in cancer cells, including apoptosis and proliferation." (PMID 28915616, 2017).
cancer (continued). "To delineate which HDAC family member(s) play an important role in repressing FBP1 expression in HCC cells, we focused our attention on HDAC1 and HDAC2 among the 18 different members of the family because they are often deregulated in human cancers." (PMID 28262837, 2017). "For example, stable LSD2 overexpression significantly increases the expression of LSD1, HDAC1, and HDAC2, which are important components of the NuRD (nucleosome remodeling and histone deacetylase) complex that has important implications in cancer biology." (PMID 29137219, 2017). "Considering the effects of HDAC2 on cell proliferation and apoptosis in cancer cells, we focused on the specific miRNA, which directly targeted HDAC2, to explore the potential therapeutic method for CRC." (PMID 28538837, 2017). "Analysis of this data shows that some epigenetic proteins such as DNMT3A, HDAC2, KDM6A, TET2 are highly mutated in most of the cancer cell lines." (PMID 26777304, 2016). "For example, HDAC1 and HDAC2 expression is often enhanced in many cancers and has been correlated with transcriptional repression of tumor suppressors, including p21." (PMID 27631103, 2016). "In our analysis, we found that epigenetic proteins DNMT3A, HDAC2, KDM6A, and TET2 are highly mutated in variety of cancers." (PMID 26777304, 2016). "Although aberrant PCAF and HDAC2 expression in the context of arsenic-induced carcinogenicity has not yet been documented, both PCAF and HDAC2 have been implicated in cancer." (PMID 25574600, 2015). "Existing data has implied that Lsh interacts predominantly with the de novo methyltransferases Dnmt3a and Dnmt3b in MEFs, while this interaction occurs by means of HDAC1 and HDAC2 in transformed cancer cells (HCT116)." (PMID 26491684, 2015). "In this study, we suggest that not only survivin downregulation plays an important role in HDAC2 inhibition-induced cell death, but targeting of the HDAC2 and survivin is the cancer selective treatment." (PMID 25605253, 2015). "An over expression of HDAC2, COX-2 and 5-LOX have been implicated in the growth and progression of various cancer types, and are also found to be regulated by the NF-κB pathway." (PMID 26158863, 2015). "And survivin and HDAC2 expression levels are mostly overexpressed in cancer patients compared to normal lung tissue." (PMID 25605253, 2015). "The present results suggest that wogonin has multiple anti-cancer effects associated with degradation of c-Myc, SKP2, HDAC1 and HDAC2." (PMID 24265759, 2013). "Although there are some reports that HDAC2 expression is dysregulated in cancer cells, only limited numbers of articles have shown in vivo analysis of HDAC2 in cancer." (PMID 22132221, 2011). "Consistently, targeted-disruption of HDAC2 elicited growth arrest and apoptosis of certain human cancer cells." (PMID 22132221, 2011). "Mutation analysis of HDAC1, HDAC2, SUV39H1, and SUV39H2 revealed only two out of 181 cancer samples (both cell lines) with significant coding-sequence alterations." (PMID 16638127, 2006). "We also screened HDAC1, HDAC2, SUV39H1, and SUV39H2 for mutations in 65 cancer cell lines and 116 primary tumours." (PMID 16638127, 2006). "Emerging evidence highlights the tumor-suppressive effects of HDAC2 depletion across cancer types." (PMID 40260239, 2025). "Among HDACs, HDAC2 emerges as a critical player due to its multifaceted roles in cancer biology." (PMID 41408324, 2025). "Especially the class I isoforms HDAC1 and HDAC2 are overexpressed in cancer." (PMID 41409164, 2025). "Consequently, the involvement of HDAC2 in epigenetic silencing of tumor suppressors and its overexpression in aggressive cancers highlight its potential as a therapeutic target." (PMID 41408324, 2025).